FAP (fibroblast activation protein alpha)
Diseases named in the same sentence as FAP in open-access papers (continued):
Sharing a sentence is not in itself a finding about the gene and the disease.
aneurysm (1 paper, 2025). Bulging or ballooning in an area of an artery secondary to arterial wall weakening. "In vivo studies, we used a PPE-induced AAA mouse model demonstrated that FAP inhibition reduced aneurysm progression and macrophage infiltration, further supporting its role in AAA pathogenesis." (PMID 40520892, 2025). "In vivo inhibition of FAP reduced aneurysm progression and macrophage infiltration, highlighting its therapeutic potential." (PMID 40520892, 2025). "While FOSB and RASSF2 have established roles in AAA literature 17, 18, our study represents the first report implicating FAP in aneurysm pathology." (PMID 40520892, 2025). "In a porcine pancreatic elastase (PPE)-induced AAA mouse model, pharmacological inhibition of FAP (Ac-Gly-BoroPro) attenuated aneurysm formation and reduced macrophage infiltration." (PMID 40520892, 2025). "After injection a FAP-specific inhibitor to the PPE-induced mouse AAA model, we observed a reduction in aneurysm size, demonstrating that FAP can promote aneurysm formation." (PMID 40520892, 2025).
angioedema (1 paper, 2024). Swelling involving the deep dermis, subcutaneous, or submucosal tissues, representing localized edema. "Additionally, Tie-2, FAP-α, tPA, sE-selectin, and Ang-2 have been identified as promising biomarkers for differentiating between hereditary angioedema, ACE inhibitor-induced angioedema, and angioedema associated with chronic spontaneous urticaria." (PMID 38543146, 2024).
appendiceal neoplasm (1 paper, 2024). A benign or malignant neoplasm involving the appendix. "Second, although previous studies have identified FAPI with a high selectivity to FAP positive tumors, immunohistochemical staining of FAP must be performed to determine the expression status of FAP in these appendiceal neoplasms." (PMID 38715096, 2024).
arteriosclerosis (1 paper, 2024). A vascular disorder characterized by thickening and hardening of the walls of the arteries. "Coronary sections with moderate postbypass coronary atherosclerosis and with heart transplant arteriosclerosis showed positive and diffuse patterns of intraluminal FAP staining with the F19 antibody." (PMID 39590809, 2024).
asthma (1 paper, 2022). "In conclusion, our study revealed that BT was effective in 81% of patients irrespective of asthma endotypes and was associated with a reduction in ACTA2 and an increase in FAP, COL1A1, COL1A2 and CD68 gene expression." (PMID 35534846, 2022).
autoimmune myocarditis (1 paper, 2026). Autoimmune myocarditis is an autoimmune disease that affects the heart. "However, their model excluded inflammatory contexts (e.g., viral or autoimmune myocarditis), where immune cell and cytokine-rich microenvironments may alter FAP+ cell susceptibility." (PMID 41356193, 2026). "Extending these findings, our work specifically addresses inflammation-driven cardiac fibrosis, FAP.CAR-T uniquely eliminates activated myofibroblasts in autoimmune myocarditis, achieving fibrosis reduction and functional recovery." (PMID 41356193, 2026).
autoimmune neurological diseases (1 paper, 2021). "However, it is also important to note that FAP is upregulated in chronic inflammation and fibrosis; therefore, distinguishing GBM from other inflammatory or autoimmune neurological diseases needs to rely on the clinical manifestations and characteristics of multimodal imaging." (PMID 34068501, 2021).
autoimmune thyroiditis (1 paper, 2024). "Here, we investigate FAP expression in the thyroid gland in autoimmune thyroiditis (AIT)." (PMID 39023777, 2024).
B-cell lymphoma (1 paper, 2025). "In addition, immunohistochemistry was used to analyze intratumoral FAP expression in tissue biopsies from a subset of B-cell lymphoma patients (n = 34)." (PMID 41373408, 2025).
benign oncocytoma (1 paper, 2026). "Some uptake differences were noted between distinct tumors, with ccRCC cases showing the highest uptake and benign oncocytoma showing lower uptake, suggesting that FAP expression may be heterogeneous across renal tumors." (PMID 41101974, 2026).
cardiac hypertrophy (1 paper, 2025). "Histological evaluations were performed across groups to determine the effects of FAP KO on myocardial hypertrophy and cardiac fibrosis." (PMID 40855978, 2025). "The findings showed that FAP knockout (KO) attenuated cardiac hypertrophy, inflammation, oxidative stress, fibrosis, cell apoptosis, and energy metabolism dysfunction." (PMID 40855978, 2025). "This study demonstrated that FAP plays a decisive role in T2DM-associated HFpEF by activating the CaMKIIδ-Calcineurin A-NFATc2 signaling pathway, ultimately promoting myocardial hypertrophy, fibrosis, inflammation, oxidative stress, apoptosis, and energy metabolism dysfunction." (PMID 40855978, 2025). "In the present study, FAP knockout (KO) attenuated the calmodulin-dependent protein kinase δ-Calcineurin A-NFATc2 signaling pathway and attenuated cardiac hypertrophy, fibrosis, inflammation, oxidative stress, apoptosis, and energy metabolism dysfunction, ultimately attenuating T2DM-induced HFpEF." (PMID 40855978, 2025). "Similarly, FAP inhibitor Talabostat reversed cardiac hypertrophy, remodeling, and oxidative stress, thereby improving T2DM-induced HFpEF." (PMID 40855978, 2025). "However, their expression levels were down-regulated following FAP KO, suggesting that myocardial hypertrophy, fibrosis, inflammation, oxidative stress, cell apoptosis, and energy metabolism dysfunction were attenuated following FAP KO in the T2DM-induced HFpEF group." (PMID 40855978, 2025).
cervical dysplasia (1 paper, 2021). "To evaluate CAF accumulation during cervical carcinogenesis, we detected α-SMA (CAF marker), fibroblast activation protein (FAP) (CAF marker), and Vimentin (fibroblast maker) levels in different grades of cervical dysplasia and CC." (PMID 33731705, 2021).
cholestasis (1 paper, 2024). Impairment of the bile flow caused by obstruction within the liver, or outside the liver in the bile duct system. "Initial PET/CT scan with [68Ga]Ga-FAP-2286 showed an intensively focal uptake in the porta hepatis in projection to the bile duct drainages, which has been assessed as a malignant tumor and the primary cause of the patient’s cholestasis." (PMID 39338305, 2024).
colonic adenomatous polyp (1 paper, 2013). "One form of risk stratification is represented by the ∼tenfold range in colonic adenomatous polyp numbers observed among individuals of FAP families that suggest a range of fetal/juvenile APC mutation rates." (PMID 24195059, 2013).
colorectal polyp (1 paper, 2023). "They found that FAP expression was higher in CRC tissues compared to colorectal polyp samples." (PMID 37316886, 2023).
cystadenofibroma (1 paper, 2023). A benign or borderline neoplasm that arises from the ovaries and the fallopian tubes. "Additionally, as cells from high-grade serous OvCa, cystadenofibroma occasionally present weak expression of CAFs markers (PDGFRα, FAP)." (PMID 37958844, 2023).
diffuse intrinsic pontine glioma (1 paper, 2020). A neuroglial tumor that arises from the middle portion of the brain stem. "A small subset (20%) of diffuse intrinsic pontine glioma (DIPG) tumors also showed elevated FAP expression." (PMID 33082953, 2020).
duodenal disorder (1 paper, 2023). Pathological conditions in the duodenum region of the small intestine (intestine, small). "Studies investigating duodenal disorders revealed only studies that examined FAP of the duodenum, while heterogeneous studies showed different doses and treatments alone or in combination with Celecoxib." (PMID 37182914, 2023).
emphysema (1 paper, 2023). "FAPα detection by immunohistochemistry was previously studied in lung tissues and showed that FAPα was not expressed in normal lung tissue nor emphysema but well in fibroblast foci and fibrotic interstitium of IPF patients." (PMID 37880678, 2023).
endometrial tumor (1 paper, 2025). "Based on expression analysis in patient-derived endometrial tumor tissues, we identify two potential targets – fibroblast activation protein (FAP) and melanoma-associated antigen A4 (MAGEA4) – for immunotherapy using an ex vivo vaccine setting." (PMID 41345672, 2025).
ependymoma (1 paper, 2020). A WHO grade II, slow growing tumor of children and young adults, usually located intraventricularly. "The frequency of FAP‐expressing tumors was highest for ependymoma, with 65.2% of tumors having FAP expression levels above the threshold." (PMID 33082953, 2020).
fibroma (1 paper, 2009). A non-metastasizing neoplasm arising from the fibrous tissue. "FAP and DPP-IV were also positive in spindle-shaped tumour cells of one non-ossifying fibroma, one chondroblastoma, and one desmoid tumour." (PMID 19817894, 2009).
giant cell tumours (1 paper, 2009). "All these components of giant cell tumours expressed FAP and DPP-IV." (PMID 19817894, 2009).
glomerulonephritis (1 paper, 2026). A renal disorder characterized by damage in the glomeruli. "When excluding the single case of glomerulonephritis with markedly increased FAP radiotracer uptake in both kidneys, the FAP radiotracer uptake in the renal background for the remaining 5 patients tended to correlate with FAP expression in the renal background (r = 0.71; P = 0.180)." (PMID 41101974, 2026).
Granuloma (1 paper, 2024). A compact, organized collection of mature mononuclear phagocytes, which may be but is not necessarily accompanied by accessory features such as necrosis. "However in CVID, reduced expression of the fibrosis-related protein fibronectin, but enrichment of CD163, CD3 and FAPα inside CVID granulomas was observed." (PMID 39373788, 2024).
Hodgkins lymphoma (1 paper, 2025). A heterogeneous group of malignant lymphoid neoplasms of B-cell origin characterized histologically by the presence of Hodgkin and Reed-Sternberg (HRS) cells in the vast majority of cases. "Elevated FAP uptake was notably higher in Hodgkin lymphoma lesions, which correlated with intense FAP immunostaining (score, 31)." (PMID 40417720, 2025).
inflammatory bone diseases (1 paper, 2025). "Fibroblast activation protein (FAP) might be a promising immunity‐regulating target in bone inflammatory diseases." (PMID 39716898, 2025). "Fibroblast activation protein (FAP), predominantly expressed in activated fibroblasts, plays a key role in inflammatory bone diseases, but its role in periodontitis remains unclear." (PMID 39716898, 2025).
intraepithelial neoplasia (1 paper, 2025). A precancerous neoplastic process that affects the squamous, glandular, or transitional cell epithelium without evidence of invasion. "Consistent with our previous findings, the content of CAFs, as indicated by the immunostaining of fibroblast activation protein (FAP), was significantly higher in GC samples than in intraepithelial neoplasia samples and normal gastric samples." (PMID 39764562, 2025).
keratoconus (1 paper, 2016). A degenerative, structural disorder of the eye, characterized by a cone-shaped protrusion of the cornea. "Decentralized expression of FAP and vimentin was visible throughout the corneas of the patients with keratoconus, and in the superficial stroma, excessive expression of FAP and vimentin was observed." (PMID 26885515, 2016). "Eight keratoconic corneal buttons harvested from the 8 advanced keratoconus patients with superficial stromal scarring underwent immunohistochemistry staining, and the scar regions expressed high immunogenicity of fibroblast activation proteins (FAP), vimentin, and α-smooth muscle actin (α-SMA)." (PMID 26885515, 2016).
leukopenia (1 paper, 2023). "It is plausible that an anti-FAP CAR T cell could induce NK cell lysis, resulting in NK cell leukopenia in humans, this toxicity might be missed in preclinical murine models." (PMID 38196606, 2023).
leukoplakia (1 paper, 2022). A white patch or plaque on a mucous membrane that cannot be characterized clinically or pathologically as any other disease. "Another study also confirmed that the leukoplakia with Candida albicans (or Candidal leukoplakia) has a high rate of cancer transformation, because it highly expressed a fibroblast activation protein (FAP) and α-smooth muscle actin (α-SMA)." (PMID 36548207, 2022).
lipoma (1 paper, 2009). A benign, usually painless, well-circumscribed lipomatous tumor composed of adipose tissue. "No tumour cells expressed FAP or DPP-IV in lipoma or elastofibroma." (PMID 19817894, 2009).
liver steatosis (1 paper, 2025). "CDH2 and FAP combined with other clinical parameters, represent useful tools for accurate diagnosis of fatty liver, emphasizing the importance of integrating novel markers into diagnostic algorithms for MASLD." (PMID 39017916, 2025). "Statistics associated with the figure reveal that the logit model achieved better diagnostic performance for liver steatosis than the components separately, particularly when comparing with the AUC of LDL (p < 0.0008), CDH2 (p < 0.0137) and FAP (0.0119), but not against FLI (p = 0.0845)." (PMID 39017916, 2025). "The current diagnostics of hepatic steatosis in pediatric subjects based on US and surrogate indexes need additional improvements, and this can be achieved with a future combination of them in novel algorithms accounting for additional protein markers such as CDH2 and FAP." (PMID 39017916, 2025).
lung diseases (1 paper, 2023). "Thus, it suggests that BALF may provide useful information for the diagnosis of various lung diseases, including BAP/FAP." (PMID 37255757, 2023).
lymphopenia (1 paper, 2025). Reduction in the number of lymphocytes. "The most common FAP-IL2v–related grade 3/4 adverse events were lymphopenia (23%), elevated γ-glutamyltransferase (8%), elevated alanine aminotransferase (6%), and infusion-related reaction (6%)." (PMID 39895413, 2025). "The most common FAP-IL2v–related AEs with a grade 3/4 severity were lymphopenia (23%), with a median duration of 4 days, followed by elevated γ-glutamyltransferase (8%), elevated ALT (6%), and IRR (6%)." (PMID 39895413, 2025).
medulloblastoma (1 paper, 2020). A malignant, invasive embryonal neoplasm arising from the cerebellum. "Medulloblastoma was also characterised by a relatively high frequency of FAP‐expressing tumors (45.5%)." (PMID 33082953, 2020).
meningioma (1 paper, 2025). A generally slow growing tumor attached to the dura mater. "FAP expression was more frequent in meningiomas of CNS WHO grade 3 (vs. CNS WHO 2; p < 0.001), and samples with NF2 mutations (p = 0.032) or CDKN2A/B deletions (p = 0.013) compared to wildtype." (PMID 39969538, 2025).
metabolic syndrome (1 paper, 2025). A cluster of metabolic risk factors for CARDIOVASCULAR DISEASES and TYPE 2 DIABETES MELLITUS. "In pathological tissues, elevated expression of FAP-α is typically detrimental; thus, inhibiting FAP-α is considered beneficial for the treatment of inflammatory diseases such as metabolic syndrome, cancer, and fibrosis." (PMID 41008517, 2025).
mucinous carcinomas (1 paper, 2022). "In this study, we demonstrated additional FAP expression in signet-ring/mucinous carcinomas, which normally exhibit low [18F]F-FDG uptake." (PMID 36698416, 2022).
myocardial diseases (1 paper, 2025). "Owing to the identification of fibroblast activation protein (FAP) as a promising target for the treatment of solid tumors, engineered CAR-T cells that recognize FAP also significantly reduce cardiac fibrosis and improve heart function in the treatment of myocardial diseases." (PMID 40481182, 2025).
neurofibroma (1 paper, 2026). An intraneural or extraneural neoplasm arising from nerve tissues and neural sheaths. "Across independent bulk datasets, FAP was consistently up-regulated in MPNSTs compared with neurofibromas." (PMID 41591566, 2026). "In clinical imaging, FAP-PET demonstrated higher tracer uptake in histologically proven MPNSTs than in benign lesions within the same patient, including a neurofibroma that was FDG-avid but FAP-negative, supporting added diagnostic specificity over FDG-PET/CT." (PMID 41591566, 2026).
NK-cell leukemia (1 paper, 2023). "Our data suggest that anti-FAP CAR cells may also be useful in NK cell malignancies such as aggressive NK-cell leukemia." (PMID 38196606, 2023).
oncocytoma (1 paper, 2026). "The median tumoral FAP radiotracer uptake was highest in patients with ccRCC (SUVmax, 3.1), followed by oncocytoma (SUVmax, 1.9) and pRCC (SUVmax, 1.1)." (PMID 41101974, 2026).
oral submucosal fibrosis (1 paper, 2024). "In oral submucosal fibrosis (OSF), FAP promotes the proliferation, migration, and activation of oral fibroblasts via the PI3K-Akt signaling pathway." (PMID 39055892, 2024).
ossifying fibroma (1 paper, 2009). A bone benign neoplasm that is located_in the mouth and results_in an overgrowth of gingival tissue due to irritation or trauma. "Among benign tumours, non-ossifying fibromas, desmoid tumours and chondroblastomas expressed both FAP and DPP-IV." (PMID 19817894, 2009).
pancreatic carcinosarcoma (1 paper, 2025). "The role of fibroblast activation protein PET (FAP-PET) in pancreatic carcinosarcoma is an emerging area of interest, given the tumor’s aggressive nature and the known limitations of conventional imaging modalities." (PMID 40862839, 2025).